PHGDH (phosphoglycerate dehydrogenase)
Diseases named in the same sentence as PHGDH in open-access papers (continued):
Sharing a sentence is not in itself a finding about the gene and the disease.
tumor (continued). "The regulation of integrin proteins by MYC and PHGDH provides a valuable insight into how oncogenes can modulate tumor cell plasticity." (PMID 39883338, 2024). "It has also been demonstrated that NRCAM, LRFN4, and PHGDH are upregulated in CRC tissues compared to normal samples around the tumor and serve as predictors of poor clinical outcomes in advanced CRC patients 42-44." (PMID 38706895, 2024). "Exogenous serine and PHGDH-mediated de novo serine synthesis are co-regulators of tumor growth and metastasis, immune cell function, etc.." (PMID 38666909, 2024). "PHGDH, an enzyme involved in cancer cell metabolism, is another oncogene with a dual role in tumor biology." (PMID 39883338, 2024). "In mice, circulating tumor cells and early metastatic lesions were found to exhibit low expression of the PHGDH protein." (PMID 38945960, 2024). "LC–MS-based metabolomics on tumor lysates demonstrated lower tumor serine and glycine levels upon deletion of SLC6A14/12A4 and SLC6A14/25A15 in HCT116 PHGDH-deficient xenografts, whereas serine and glycine levels in the circulating blood remained unaltered." (PMID 38066114, 2023). "Consistently, re-introduction of PHGDH-T57A decreased tumor numbers and volumes in the mouse HCC models." (PMID 37726403, 2023). "The enzyme PHGDH is regulated by the tumor suppressors RNF5 and Parkin, proteins that function as E3 ubiquitin ligases." (PMID 37949226, 2023). "Exogenous serine and PHGDH-mediated serine biosynthesis play important roles in promoting tumor cell growth, regulating adaptive immunity and antiviral innate immunity." (PMID 36899022, 2023). "CRL4ADCAF16 complex catalyzes the mono-ubiquitination of PHGDH at K146, thereby enhances PHGDH activity to upregulate S-adenosylmethionine and promotes tumor cell migration." (PMID 38104139, 2023). "Metabolomic and transcriptomic analyses of human and mouse GBM showed that the expression of PHGDH and the metabolism of serine were significantly altered in tumor endothelial cells." (PMID 38111705, 2023). "NCT-503, a PHGDH inhibitor, significantly attenuated tumor progression in CRC patient-derived xenograft tumors and suppressed tumor cell growth in a dose-dependent manner." (PMID 36755301, 2023). "PHGDH ablation was shown to prune aberrant tumor vessels in vivo, allowing for improved infiltration and activation of T cells." (PMID 38132354, 2023). "As a result, a significant promotion of tumor growth in the PHGDH-R135W-expressing mice was observed." (PMID 37726403, 2023). "The PHGDH-mediated pathway promotes endothelial cell overgrowth, with a resulting immune-hostile microenvironment that limits T-cell infiltration into the tumor bed and subsequent activation." (PMID 38132354, 2023). "As a result, primary tumor development was unaffected by genetic and pharmaceutical reduction of PHGDH, while brain metastasis was reduced." (PMID 38292487, 2023). "To further verify the function of PHGDH in vivo, we used Ishikawa cells to construct a subcutaneous tumor‐bearing model in nude mice." (PMID 37387559, 2023). "In this study, a new nomogram prediction model was constructed using age, clinical stage, histologic grade, tumor aggressiveness, histologic type, and PHGDH levels as indicators, using which can improve the accuracy of identifying high-risk patients." (PMID 36803157, 2023). "The mice were treated with MET/CAT to induce hepatocarcinogenesis with the accumulated nuclear PHGDH in tumor tissue." (PMID 37078828, 2023). "Dietary restriction of serine or phosphoglycerate dehydrogenase depletion mitigates tumor growth and extends the survival of tumor patients." (PMID 37187454, 2023). "More considerably, nuclear localization of PHGDH correlated with a poorer prognosis, suggesting that PHGDH functionally contributes to tumor progression in a location‐dependent manner." (PMID 37078828, 2023).
tumor (continued). "Still, its primary site of localization changes from the cytosol to the nuclear, with the intensity of nuclear PHGDH dramatically increased in tumor tissue." (PMID 37078828, 2023). "In most cases, an increase in the level of PHGDH promotes the proliferation of tumor cells, whereas tumor cell proliferation is inhibited when PHGDH is knocked down or mutated at specific sites." (PMID 38139250, 2023). "Recent studies have shown that PHGDH is upregulated in Ras mutant tumor patient-derived xenografts of the acquired MAP/ERK kinase–resistant inhibitor PD901." (PMID 37187454, 2023). "The protein expression of PHGDH was increased in tumor samples compared to the paired para‐tumoral sites in five patients as shown in IHC staining." (PMID 37387559, 2023). "CBR-5884 is one kind of PHGDH inhibitor that have been reported and played a tumor suppressing role in breast cancer." (PMID 36105480, 2022). "Targeting PHGDH in the one-carbon metabolism has been shown to delay tumor progression, though more studies are needed to confirm it." (PMID 35935878, 2022). "CBR-5884 is another recently developed small molecular inhibitor of PHGDH, which shows a high selective toxicity to PHGDH-dependent tumor cells." (PMID 35216362, 2022). "A significant transcriptional upregulation of Phgdh was observed in tumour bearing mice, and immunohistochemical analyses detected PHGDH in parenchymal cells and also in CCA lesions." (PMID 35619118, 2022). "Based on the data retrieved from the TCGA database, the results indicated that the PHGDH expression was significantly higher in tumor tissues than in the adjacent tissues." (PMID 36147463, 2022). "Accordingly, in TAA-elicited tumours we found marked elevations not only in the expression of key genes driving glycolysis but also of PHGDH." (PMID 35619118, 2022). "Immunofluorescence of mouse subcutaneous tumor tissue also confirmed the down-regulation of PCBP2 protein expression after the knock-down of PHGDH." (PMID 36147463, 2022). "In the current study, we have screened the natural products library against PHGDH by computational screening to identify metabolic inhibitors for PHGDH-amplified tumor types." (PMID 36144843, 2022). "This was then combined with an anti-tumor model (PHGDH enzyme inhibition animal model) to set up a novel exogenous and/or endogenous serine deficient pregnant rat model." (PMID 36185664, 2022). "An increased expression of PHGDH at mRNA and protein levels in tumor tissues compared to matched adjacent non-tumor tissues was previously identified." (PMID 35805008, 2022). "PHGDH knockout or inhibition slowed down cell proliferation, and then promoted drug resistance of tumor cells to chemotherapy." (PMID 35629893, 2022). "For determining the effect of PHGDH expression on the malignant progression of BCa, a subcutaneous tumor formation was initiated in nude mice." (PMID 36147463, 2022). "Lastly, it is reported that Hsa_circ_0062682, a serum and serine starvation-induced circRNA, promotes serine metabolism and tumor growth via miR-940/PHGDH axis in colorectal cancer." (PMID 35842651, 2022). "PHGDH reportedly modulates FoxM1 expression, thus promoting the expression of the cell proliferation marker gene cyclin D1 and the proliferation of tumor cells." (PMID 35344765, 2022). "When serine is limiting, augmented SBP, especially PHGDH, provides a growth advantage for tumor proliferation via sufficient serine in breast cancer and melanoma compared with normal environmental serine levels." (PMID 36582785, 2022). "The expression of PSPH and SHMT2 was significantly higher in tumour tissues, whereas PHGDH and PSAT1 were reduced." (PMID 36110969, 2022). "Evidence also indicates that PHGDH affected the proliferation and polarization of macrophages to regulate the tumor immune microenvironment." (PMID 36147463, 2022). "The immunohistochemical staining of tumor tissues between two groups showed that PHGDH and Ki67 expressions were inhibited in CBR-5884 group." (PMID 36105480, 2022).
tumor (continued). "Compared with single drug, PHGDH inhibitor combined with gemcitabine/cisplatin can achieve synergistic tumor inhibition." (PMID 35629893, 2022). "Together, these data confirm that circ_0062682 knockdown inhibits CRC tumor growth in vivo via the miR-940/PHGDH axis." (PMID 34957102, 2021). "In this study we examine the cooperation between serine and glycine starvation (-SG) and PHGDH inhibition (PHGDHi), demonstrating a reduction of tumour cell growth in vitro and in vivo." (PMID 33446657, 2021). "Taken together, these data demonstrate, for the first time, that circ_0062682 promotes serine metabolism and tumor growth in CRC by regulating the miR-940/PHGDH axis, suggesting circ_0062682 as a potential novel therapeutic target for CRC." (PMID 34957102, 2021). "In this study, we reported for the first time that circ_0062682, as a stress-induced circRNA, is able to promote serine synthesis and tumor growth by regulating the miR-940/PHGDH axis." (PMID 34957102, 2021). "To examine these responses to dietary serine/glycine starvation and PHGDH inhibition in vivo, we first examined purine levels in the tumours." (PMID 33446657, 2021). "Immunohistochemistry analysis of these tumours revealed that feeding mice with a -SG diet led to a clear induction of PSAT1 – and to a lesser extent PHGDH – in tumours, indicating the induction of an ATF-4 response in vivo." (PMID 33446657, 2021). "PHGDH downregulation significantly inhibited cell proliferation, and the combined treatment between PHGDH inhibitor and gemcitabine/cisplatin achieved synergistic tumor suppressive effect compared to each single agent group both in vitro and in vivo." (PMID 32386122, 2020). "Considering these factors, the targeted inhibition of PHGDH in tumor patients with high PHGDH expression will face significant challenges." (PMID 32226297, 2020). "Intriguingly, NCT-502, a chemical inhibitor of PHGDH, significantly increased invasion of tumor spheres derived from PHGDH-active GBM cell lines into 3D matrix." (PMID 32620753, 2020). "It is important to identify at what time point PHGDH expression is high during tumorigenesis, how PHGDH promotes tumorigenesis and metastasis, and the relationship between PHGDH and tumor resistance." (PMID 32226297, 2020). "PHGDH is significantly overexpressed in HIF2α knockout tumours, as well as tumours that have shown sunitinib resistance." (PMID 33511334, 2020). "PHGDH inhibition with CBR-5884 inhibited tumour cell growth in all tested cell lines in a dose-dependent manner." (PMID 32203214, 2020). "Under serum containing culture conditions serine and glycine deprivation alone led to a significant decrease of tumour cell proliferation in LN-308 cells with an intrinsically low PHGDH expression." (PMID 32203214, 2020). "A PHGDH inhibitor, CBR-5884, has been found to dampen the proliferation of PHGDH-dependent TNBC tumor cells." (PMID 32296646, 2020). "The direct inhibition of PHGDH by small-molecule inhibitors results in a decrease in cellular proliferation in vitro, with marginal inhibition of tumour growth in vivo." (PMID 33511334, 2020). "Our investigation of BC revealed that the expression level of PHGDH was correlated with tumor grade and prognosis." (PMID 32386122, 2020). "Favorable prognosis of PHGDH-high tumors was further validated in 42 independent IDH wild-type GBM tumors assessed by immunohistochemistry on a tumor tissue microarray (SMC-TMA) using an anti-PHGDH antibody." (PMID 32620753, 2020). "The mechanisms of PHGDH amplification promoting tumor growth include supplying serine for protein synthesis and one-carbon metabolism, promoting the TCA cycle, and non-enzymatic functions including FOXM1 binding." (PMID 32226297, 2020). "Inhibition of PHGDH also results in a series of metabolic adaptations that can acutely sensitize tumour cells to various chemotherapies." (PMID 33511334, 2020).
tumor (continued). "The good prognosis of the PHGDH-high group suggests a functional role for PHGDH in limiting tumor aggressiveness." (PMID 32620753, 2020). "Inhibiting the interactions of PHGDH/eIF4A1 and PHGDH/eIF4E will provide potential targets for anti-tumor therapeutics development." (PMID 30744688, 2019). "In fact, NT cells treated with IL-10 produced tumor activator factors such as RhoA, the glia maturation factor beta, galectin-1, the isocitrate dehydrogenase subunit alpha, and the D-3-phosphoglycerate dehydrogenase." (PMID 31766635, 2019). "The results of in vivo studies further identified that PHGDH overexpression converted the tumor to a more highly developing state and the overall survival of orthotopic xenograft mouse model was further shortened." (PMID 30744688, 2019). "Several academic laboratories and pharmaceutical companies have developed PHGDH inhibitors that have shown efficacy in some tumor models." (PMID 31096630, 2019). "Orthotopic xenograft model showed that PHGDH knockdown reduced the metastases of primary tumor to liver and lung and significantly prolonged the survival of tumor bearing nude mice compared with control." (PMID 30744688, 2019). "Knockdown of PHGDH significantly attenuated the tumor growth and prolonged the survival of tumor bearing mice." (PMID 30744688, 2019). "PNLIPRP1 and GNMT have been documented as the tumor suppressor genes of PC and PHGDH been certified as the tumor promoter gene of PC." (PMID 31706267, 2019). "Mechanisms whereby tumours sustained HT under CD44-knockdown conditions include upregulation of PHGDH, PSAT1 and PSPH that drove glycolysis-dependent activation of serine/glycine-cleavage systems to provide one-methyl group for HT synthesis." (PMID 29674746, 2018). "Among all genes in the focal amplifications, only five (TBX15, NOTCH2, PTGFRN, CNN3, and PHGDH) showed appreciably higher expression levels than those observed in tumor samples from the TCGA database." (PMID 28977029, 2017). "In agreement, PHGDH mRNA was found to be a marker of basal tumours as a part of the PAM50 signature." (PMID 26725330, 2016). "A significant finding is the tumour specific expression of 3- phosphoglycerate- dehydrogenase which catalyses the production of 3-phosphoglycerate." (PMID 25872475, 2015). "Chk2 and cyclin D1, hallmarks of tumor proliferation, were also downregulated after PHGDH knockdown." (PMID 23229761, 2013). "In the 132 tumor samples, 90 exhibited high PHGDH expression levels (68.2 %), and 42 exhibited low expression levels (31.8 %)." (PMID 23229761, 2013). "PHGDH is a crucial metabolic enzyme in the serine biosynthesis pathway, and upregulation of PHGDH resulted in increase of tricarboxylic acid cycle, increase of glutathione production, and the promotion of tumor growth." (PMID 41492362, 2026). "Importantly, pharmacological inhibition of HNRNPU K181 lactylation by Pazopanib suppresses PHGDH expression and tumor growth, underscoring its translational potential." (PMID 42201673, 2026). "In addition, we investigated the relationships among the tumor stemness score determined with the TCGAbiolinks algorithm, the PHGDH transcription level, and the serine metabolic pathway score determined through GSVA in the TCGA-GBM cohort." (PMID 40102981, 2025). "Abnormal expression of PHGDH and PSPH may enhance serine synthesis in tumor cells, positioning them as potential diagnostic biomarkers." (PMID 40265021, 2025). "Thus, subsequent work is imperative to unravel the intricate mechanisms by which PHGDH modulates diverse target genes and their consequential implications for tumor progression." (PMID 40681503, 2025). "Parkin, a tumor suppressor, ubiquitinates PHGDH at K330, with its IBR domain binding to PHGDH-SBD2." (PMID 40598535, 2025). "Although, targeting PHGDH may inhibit tumor growth, but its impact on the immune response remains unclear." (PMID 41179661, 2025).
tumor (continued). "Targeting serine metabolism, particularly via PHGDH inhibition, not only suppresses tumor growth through nutrient deprivation but also crucially blocks compensatory pro-metastatic adaptations mediated by the SSP that can be triggered by other therapies, such as chemotherapy." (PMID 41415540, 2025). "In the CGGA database, we also noted a consistent positive association between the tumor stemness score and the PHGDH expression level, regardless of tumor grade." (PMID 40102981, 2025). "Moreover, the tumor-promoting effect of PHGDH was markedly reversed by shRNA- or sotrastaurin-mediated intervention targeting PRKCD." (PMID 40681503, 2025). "In addition, PHGDH also participates in tumor progression, metabolic diseases and immune-related diseases." (PMID 40383841, 2025). "Furthermore, genetic ablation or pharmacological inhibition of PHGDH markedly reduced tumor growth and increased tumor sensitivity to radiotherapy, thereby improving survival outcomes in orthotopic GSC-derived and patient-derived GBM xenograft models." (PMID 40102981, 2025). "Notably, while PHGDH exhibits heterogeneous expression in tumour cells, its expression in the GCs of TLSs is more frequent and uniform." (PMID 40660426, 2025). "However, nanomaterial-based delivery strategies for PHGDH inhibitors face challenges in completely depleting all sources of serine within tumors, as tumor cells can still import exogenous serine to partially sustain their growth." (PMID 41415540, 2025). "In tumor cells, approximately 10% of the glycolytic intermediate 3-phosphoglycerate is oxidized into the serine precursor 3-phosphohydroxypyruvate in a reaction catalyzed by phosphoglycerate dehydrogenase (PHGDH) using NAD+ as a cofactor." (PMID 41488002, 2025). "Overexpression of PHGDH has been observed in NSCLC and is associated with enhanced tumor growth." (PMID 40469185, 2025). "Therefore, the presence of PHGDH heterogeneity in primary tumors can be considered a marker of tumor aggressiveness." (PMID 39973065, 2025). "Consequently, combining CB‐839 with phosphoglycerate dehydrogenase (PHGDH) inhibition using NCT‐503 or BI‐4916 synergistically suppressed tumor growth." (PMID 40552664, 2025). "Within this context, PHGDH may support the activation and maintenance of anti‐tumour immune cell functions, especially those of plasma cells." (PMID 40660426, 2025). "However, due to the lack of research models that accurately simulate tumors in vivo, the strategy of interfering with serine metabolizing enzymes such as PHGDH is still insufficient for anti-tumor therapy." (PMID 39670663, 2025). "Additionally, PHGDH is involved in shaping the tumor microenvironment by orchestrating endothelial cell metabolism within GBM." (PMID 40102981, 2025). "In addition to this recently identified distinct subcellular localization, PHGDH is known to exhibit pronounced dynamic heterogeneity in its expression over tumor progression." (PMID 40640948, 2025). "In contrast, in the immunologically ‘cold’ MSI‐L/MSS tumours, high PHGDH expression appears to primarily promote tumour cell proliferation and may also enhance the activity of immunosuppressive cells, such as fibroblasts and M2 macrophages." (PMID 40660426, 2025). "Taken together, our findings indicate that the loss of PHGDH not only results in reduced TAM infiltration in younger mice and a restrained immunosuppressive phenotype but also leads to the inhibition of tumor growth and partial restoration of antitumor immunity." (PMID 38409249, 2024). "Interestingly, the effect of ASS1 knockout to promote tumor growth was largely abrogated by PHGDH knockout." (PMID 38710705, 2024). "Notably, conditional depletion of PHGDH resulted in a decrease in the serum level of αKG in tumor-bearing mice." (PMID 38409249, 2024). "In addition, NCT-503, a PHGDH inhibitor, has been reported to reduce cell proliferation and tumor growth in thyroid cancer." (PMID 38331894, 2024).